DDB2 (damage specific DNA binding protein 2)
Description:
Protein, which is both involved in DNA repair and protein ubiquitination, as part of the UV-DDB complex and DCX (DDB1-CUL4-X-box) complexes, respectively. Core component of the UV-DDB complex (UV-damaged DNA-binding protein complex), a complex that recognizes UV-induced DNA damage and recruit proteins of the nucleotide excision repair pathway (the NER pathway) to initiate DNA repair. The UV-DDB complex preferentially binds to cyclobutane pyrimidine dimers (CPD), 6-4 photoproducts (6-4 PP), apurinic sites and short mismatches. Also functions as the substrate recognition module for the DCX (DDB2-CUL4-X-box) E3 ubiquitin-protein ligase complex DDB2-CUL4-ROC1 (also known as CUL4-DDB-ROC1 and CUL4-DDB-RBX1). The DDB2-CUL4-ROC1 complex may ubiquitinate histone H2A, histone H3 and histone H4 at sites of UV-induced DNA damage. The ubiquitination of histones may facilitate their removal from the nucleosome and promote subsequent DNA repair. The DDB2-CUL4-ROC1 complex also ubiquitinates XPC, which may enhance DNA-binding by XPC and promote NER. The DDB2-CUL4-ROC1 complex also ubiquitinates KAT7/HBO1 in response to DNA damage, leading to its degradation: recognizes KAT7/HBO1 following phosphorylation by ATR. [Isoform D1]: Inhibits UV-damaged DNA repair. [Isoform D2]: Inhibits UV-damaged DNA repair.
Synonyms: DDBb; UV-DDB2; FLJ34321; XPE
Tractability: Small molecule: it has a high-quality binding pocket. PROTAC: UniProt records ubiquitination sites on it; ubiquitination databases record sites on it; its protein half-life has been measured.
Gene: Protein-coding gene on chromosome 11 (47,214,457 to 47,239,240, forward strand). Ensembl gene ENSG00000134574.
Subcellular location: Nucleus; Chromosome
Subcellular location (Human Protein Atlas): Cell Junctions; Nucleoplasm
Pathways (Reactome):
DNA Repair: DNA Damage Recognition in GG-NER; Dual Incision in GG-NER; Formation of Incision Complex in GG-NER
Metabolism of proteins: Neddylation; Ub-specific processing proteases
Gene Ontology:
Molecular function: damaged DNA binding; protein binding; protein-containing complex binding; ubiquitin-protein transferase activity; DNA binding
Biological process: cellular response to UV; DNA damage response; nucleotide-excision repair; protein autoubiquitination; protein polyubiquitination; response to UV; UV-damage excision repair; DNA repair; protein ubiquitination
Cellular component: chromosome; Cul4-RING E3 ubiquitin ligase complex; Cul4A-RING E3 ubiquitin ligase complex; Cul4B-RING E3 ubiquitin ligase complex; nucleoplasm; nucleus; protein-containing complex; site of DNA damage; chromatin
Genetic constraint (gnomAD): Loss-of-function variants: 29 observed, 54.99 expected, observed/expected ratio (o/e) 0.53, 90% interval 0.39 to 0.72. The upper end of that interval is the gene's LOEUF score, 0.72, which puts it in group 2 of 6, group 1 being the genes least tolerant of losing a copy. Missense variants: 424 observed, 574.24 expected, observed/expected ratio (o/e) 0.74, 90% interval 0.68 to 0.8. Synonymous variants: 176 observed, 216.27 expected, observed/expected ratio (o/e) 0.81, 90% interval 0.72 to 0.92.
Gene-disease validity (ClinGen):
ClinGen rates the evidence that DDB2 causes each of these diseases.
xeroderma pigmentosum group E (autosomal recessive): Definitive. An autosomal recessive genetic disorder caused by mutations in the DDB2 gene.
Cancer hallmarks: escaping programmed cell death (suppresses); invasion and metastasis (suppresses); proliferative signalling (promotes); genome instability and mutations (suppresses)
Homologues: Orthologues: chimpanzee DDB2 (100% identical), dog DDB2 (86% identical), pig DDB2 (86% identical), rabbit DDB2 (84% identical), mouse Ddb2 (78% identical), rat Ddb2 (73% identical), guinea pig DDB2 (58% identical), tropical clawed frog ddb2 (55% identical), zebrafish ddb2 (44% identical).
Diseases named in the same sentence as DDB2 in open-access papers:
DDB2 is named in the same sentence as 73 diseases in open-access papers, as found by Europe PMC text mining. Sharing a sentence is not in itself a finding about the gene and the disease. The quoted sentences say what the papers report.
breast carcinoma (21 papers, 2009 to 2025). "To further validate the causal role of DDB2 in chemoresistance, we silenced DDB2 expression using shRNA in high-expressing breast cancer cell lines (T-47D, BT-474, and MCF7)." (PMID 41208896, 2025). "The levels of lincRNA-p21 are positively associated with the response of breast cancer patients to neoadjuvant chemotherapy and show an inverse relationship with ER status and DDB2 levels." (PMID 39479021, 2024). "DDB2 also modulates nanomechanical properties and stiffness of the mammary cancer cells associated with changes in the cortical actin–cytoskeleton organization and a loss of adhesion capacity." (PMID 31635251, 2019). "Elevated expression of DDB2 has been linked to enhanced DNA repair capacity and poor clinical responses to DNA alkylating or interstrand cross-link agents in melanoma 11, glioblastoma 12, lung 13, and breast cancers." (PMID 41208896, 2025). "Overexpression of DDB2 has opposing effects in ER+ and ER- breast cancer cells and could be one reason by NRMT1 loss differentially affects ER+ and ER- cell lines." (PMID 25909287, 2015). "Together, these findings indicate the critical role of DDB2 in promoting chemoresistance through enhanced DNA repair and suppression of DNA damage-induced apoptosis in breast cancer cells." (PMID 41208896, 2025). "In this study, we identify DDB2 as a key player in chemoresistance across multiple cancer types, including breast cancer, liver cancer, lung cancer, and cholangiocarcinoma." (PMID 41208896, 2025). "Collectively, our findings indicate DDB2 as a critical mediator of chemoresistance through its role in facilitating DNA repair and suppressing apoptosis following chemotherapy in breast cancer, lung cancer, liver cancer, and cholangiocarcinoma." (PMID 41208896, 2025). "In ovarian and breast cancer, DDB2 up-regulates IkBα, an inhibitor of NF-kB, and interacts with TGF-β1 signalling pathways, inhibiting cancer cell EMT." (PMID 38773406, 2024). "In ovarian and prostate cancers, DDB2 has demonstrated antiproliferative activities, whereas it has been observed to promote breast cancer cell proliferation." (PMID 39333096, 2024). "For example, circPFKFB4 inhibits DDB2 degradation in breast cancer and circ_0006156 binds and stabilizes S100A9 in prostate cancer." (PMID 37340423, 2023). "The hazard ratio of five genes (RBBP8,PARP3, ENDOV, UBE2V2, and DDB2) was <1, which plays a protective role in developing breast cancer." (PMID 36713553, 2022). "In the two studied PDAC cell models, DDB2 seems to be a negative regulatory factor of migration and invasion, as previously observed in breast cancer." (PMID 36568213, 2022). "Given the role of DDB2 in DNA repair, its deletion increases the sensitivity of breast cancer, HNSCC, and other cancer cells to genotoxic therapies such as PARPi (ADP-ribose polymerase inhibitors), the chemotherapeutic drug cisplatin, and radiotherapy." (PMID 36190612, 2022). "In breast cancer, DDB2 is overexpressed in non-invasive cells compared to invasive cells and DDB2 re-expression in invasive breast cancer cells limits their motility and invasiveness." (PMID 36568213, 2022). "In breast cancer and ovarian teratoma tissues, high level of DDB2 was along with lower level of CDT2." (PMID 33557942, 2021). "DDB2 is low expressed in skin cancer, breast cancer, colon cancer, prostate cancer, and ovarian cancer." (PMID 33557942, 2021). "DDB2 can suppress the invasion of breast cancer by decreasing NF-κB activity and indirectly suppresses ovarian cancer proliferation." (PMID 28212551, 2017). "In breast cancer, although DDB2 showed putative oncogenic behaviour by promoting cell-cycle progression, it was not over-expressed in ER-negative breast cancer cells, e.g. SKBR3." (PMID 28288164, 2017).
breast carcinoma (continued). "Several studies have shown that DDB2 acts a role as a tumor suppressor in a wide range of cancers, including UV-induced skin cancers, ovarian cancer, breast cancer and colon cancer." (PMID 28212551, 2017). "DDB2 was shown to act as a haploinsufficient tumor suppressor, but to complicate the issue further, DDB2 is expressed at higher levels in estrogen receptor positive breast cancer cells, and its knockdown negatively impacts the growth rate of these cells." (PMID 20374651, 2010). "Similar phenomena have been observed for genes like DDB2 in breast cancer and IDH1 in glioblastoma." (PMID 40427755, 2025). "Furthermore, DDB2 has been demonstrated to reduce breast cancer cell motility and invasiveness, while DDB2 has been found to promote migration and invasion of gastric cancer cells." (PMID 39333096, 2024). "In addition, DDB2 reduces motility and invasiveness of breast cancer cells and represses epithelial-to-mesenchymal transition (EMT) in colon cancer and in oral/head and neck squamous cell carcinoma (HNSCC)." (PMID 36568213, 2022). "In this context, it could be of interest to study NF-κB pathway in our PDAC cell models in order to determine whether DDB2 can modulate invasion through the same mechanisms than in breast cancer." (PMID 36568213, 2022). "To further investigate whether the role of CDT2 and DDB2 in cancer patients were related to DDB2 mediated CDT2 degradation, we analyzed expression of CDT2 and DDB2 in ovarian teratoma and breast cancer tissues using immunohistochemistry." (PMID 33557942, 2021). "Indeed, previous studies show that DDB2 is downregulated in metastatic colorectal and breast cancers." (PMID 32722430, 2020). "The loss of DDB2 allows the rise of LRH-1 levels which may contribute to the development of some cancers such as colon and breast cancers." (PMID 30923324, 2019). "Interestingly, in another hormone-related cancer, breast cancer, overexpression of DDB2 has been reported in tumors of the non-invasive type and another study demonstrated that the expression of DDB2 is higher in ER-positive than ER-negative breast tumors." (PMID 28212551, 2017). "In addition, DDB2 may be involved in cell adhesion by modulating membrane mechanical properties in mammary cancer cells and promoting proliferation in breast cancer cells." (PMID 38773406, 2024). "In total, 11 DNA repair genes (UBE2A, RBBP8,RAD50, FAAP20, RPA3, ENDOV, DDB2, UBE2V2,MRE11, RRM2B, andPARP3) were preserved as prognostic genes to estimate risk score, which was applied to establish the prognostic model and stratified breast cancer patients into two groups with high or low risk." (PMID 36713553, 2022). "In breast cancer (BRCA), DDB2 mRNA was enriched in ER-positive tumors within The Cancer Genome Atlas (TCGA) and GSE50948 datasets, particularly in luminal subtypes." (PMID 41208896, 2025). "A total of 11 DNA repair genes, namely, UBE2A, RBBP8,RAD50, FAAP20, RPA3, ENDOV, DDB2, UBE2V2,MRE11, RRM2B, andPARP3, were involved in the prognostic model for breast cancer patients." (PMID 36713553, 2022). "It is reported that DDB2 transcriptional regulates IκBα and SOD2 in breast cancer cells, and Snail, Zeb1 and VEGF in colon cancer." (PMID 33557942, 2021). "A binding site for DDB2 has been identified at position −230, and it is thought that DDB2 represses SOD2 transcription in breast cancer cells through interaction with AP-2, inhibiting the recruitment of Sp1 to the promoter." (PMID 29099803, 2017). "The expression level ofPARP3, RBBP8, and DDB2 was higher in breast cancer patients without HER2 receptors than in patients positive for the HER2 receptor." (PMID 36713553, 2022). "High levels of DDB2 protein and mRNA are reported in ER (Estrogen receptor)-positive and non-invasive breast cancer models compared to ER-negative aggressive breast cancer cells and mammary non-malignant cells." (PMID 31635251, 2019).
breast carcinoma (continued). "The inverse correlation between SOD2 and DDB2 expression in breast cancer patient-derived samples further establishes DDB2 as a negative transcriptional regulator." (PMID 29099803, 2017). "It is worth noting that ER-positive breast cancer cells are not sensitive to chemotherapy, which may be related to the ERα-mediated upregulation of DDB2 expression." (PMID 36190612, 2022). "The expression level of DDB2, RPA3,RAD50, RRM2B, and UBE2A was higher in breast cancer tissues with lymph node metastasis compared with breast cancer tissues without lymph node metastasis, which was estimated by the distribution of their expression level between N0 and N1–N3 stages." (PMID 36713553, 2022).
ovarian carcinoma (20 papers, 2011 to 2025). A malignant neoplasm originating from the surface ovarian epithelium. "NEDD4L has emerged as an interesting and important target gene of DDB2 as it is found to be associated with the prognosis of ovarian cancer patients." (PMID 26130719, 2015). "The expression of DNA damage-binding protein 2 (DDB2) has been linked to the prognosis of ovarian cancer and its underlying transcription regulatory function was proposed to contribute to the favorable treatment outcome." (PMID 26130719, 2015). "Here, in this study, we have demonstrated that in DDB2-deficient ovarian cancer cells, phosphorylated Smad2 was hardly increased by TGF-β treatment." (PMID 26130719, 2015). "We have previously reported that the acquisition of resistance to cisplatin in ovarian cancer cell line CP70 occurs concomitantly with the loss of DDB2 expression." (PMID 26130719, 2015). "Low expression of DDB2 is associated with skin cancer, ovarian cancer, and high-grade colon cancer." (PMID 30923324, 2019). "In addition, lower DDB2 expression is also associated with a poor outcome in patients with ovarian cancer." (PMID 26130719, 2015). "DDB2 enhances TGF-β signal transduction by downregulating NEDD4L transcription to inhibit ovarian cancer cell proliferation." (PMID 38027016, 2023). "Some studies reveal the protective role of DDB2 for ovarian cancer progression and recurrence by limiting the cancer stem cell (CSC) population." (PMID 31635251, 2019). "In an ovarian cancer cell model, DDB2 is reported to negatively regulate NEDD4L (Neural precursor cell expressed developmentally downregulated gene 4-like) cellular levels by inducing histone H3 trimethylation at the NEDD4L promoter region." (PMID 31635251, 2019). "DDB2 also represses ovarian cancer cell dedifferentiation by inhibiting the transcription of aldehyde dehydrogenase 1 family member A1 (ALDH1A1)." (PMID 31635251, 2019). "To ascertain the role of DDB2 in the regulation of ALDH1A1 expression, we overexpressed DDB2 in ovarian cancer cell lines possessing low DDB2 expression, or downregulated DDB2 in ovarian cancer cell lines possessing high DDB2 expression." (PMID 29752431, 2018). "Our previous study has demonstrated that the CSC subpopulation in ovarian cancer can be limited by DNA damage-binding protein 2 (DDB2)." (PMID 29752431, 2018). "Taken together, our data clearly demonstrate that enhanced ALDH1A1 expression plays a crucial role in DDB2 silencing-promoted ovarian cancer cell dedifferentiation." (PMID 29752431, 2018). "As a consequence, the transcription of the ALDH1A1 gene is repressed in ovarian cancer cells possessing high levels of DDB2." (PMID 29752431, 2018). "This DDB2-mediated suppression of cancer cell dedifferentiation was also confirmed in another ovarian cancer cell line SKOV3 possessing Dox-inducible DDB2 overexpression." (PMID 29752431, 2018). "We transfected Tet-On pTRIPZ-inducible shDDB2 plasmids into an ovarian cancer cell line 2008, established two Tet-On-inducible DDB2 downregulation cell lines, 2008-pTRIPZ-shDDB2, and confirmed the effect of DDB2 silencing on the expansion of CSC population." (PMID 29752431, 2018). "Taken together, these data indicate that inhibition of ALDH1A1 activity is able to reduce the CSC subpopulation, particularly in the ovarian cancer cell population with low DDB2 expression." (PMID 29752431, 2018). "Our findings have revealed, for the first time, that DDB2 is actively involved in regulating the response of ovarian cancer cells to TGF-β stimulation via NEDD4L." (PMID 26130719, 2015). "Given that NEDD4L plays an important role in constraining transforming growth factor β signaling by targeting activated Smad2/Smad3 for degradation, we investigated the role of DDB2 in the regulation of TGF-β signaling in ovarian cancer cells." (PMID 26130719, 2015).